FUNDC1 (FUN14 domain containing 1)
Description:
Integral mitochondrial outer-membrane protein that mediates the formation of mitochondria-associated endoplasmic reticulum membranes (MAMs). In turn, mediates angiogenesis and neoangiogenesis through interference with intracellular Ca(2+) communication and regulation of the vascular endothelial growth factor receptor KDR/VEGFR2 expression at both mRNA and protein levels. Also acts as an activator of hypoxia-induced mitophagy, an important mechanism for mitochondrial quality and homeostasis, by interacting with and recruiting LC3 protein family to mitochondria. Mechanistically, recruits DRP1 at ER-mitochondria contact sites leading to DRP1 oligomerization and GTPase activity to facilitate mitochondrial fission during hypoxia. Additionally, plays a role in hepatic ferroptosis by interacting directly with glutathione peroxidase/GPX4 to facilitate its recruitment into mitochondria through TOM/TIM complex where it is degraded by mitophagy.
Synonyms: MGC51029
Tractability: Antibody: UniProt predicts a signal peptide or a membrane-spanning region. PROTAC: UniProt records ubiquitination sites on it; ubiquitination databases record sites on it; its protein half-life has been measured.
Gene: Protein-coding gene on chromosome X (44,523,639 to 44,542,972, reverse strand). Ensembl gene ENSG00000069509.
Subcellular location: Mitochondrion outer membrane
Pathways (Reactome):
Autophagy: Receptor Mediated Mitophagy
Gene Ontology:
Molecular function: protein binding
Biological process: autophagy of mitochondrion; mitochondrial fusion; mitophagy; response to hypoxia
Cellular component: mitochondrial outer membrane; mitochondrion
Homologues: Orthologues: chimpanzee FUNDC1 (100% identical), macaque FUNDC1 (99% identical), rabbit FUNDC1 (99% identical), dog FUNDC1 (97% identical), guinea pig FUNDC1 (97% identical), mouse Fundc1 (96% identical), rat Fundc1 (96% identical), pig FUNDC1 (92% identical), tropical clawed frog fundc1 (81% identical), zebrafish fundc1 (72% identical), Caenorhabditis elegans fndc-1 (26% identical). Paralogues in human: FUNDC2 (56% identical).
Diseases named in the same sentence as FUNDC1 in open-access papers:
FUNDC1 is named in the same sentence as 105 diseases in open-access papers, as found by Europe PMC text mining. Sharing a sentence is not in itself a finding about the gene and the disease. The quoted sentences say what the papers report.
Obesity (24 papers, 2020 to 2026). Accumulation of substantial excess body fat. "For instance, FUNDC1 deficiency impairs mitochondrial quality and exacerbates diet-induced obesity and metabolic syndrome, Parkin regulates obesity by coordinating mitophagy, and YBX1 promotes brown adipogenesis and thermogenesis through mitophagy." (PMID 41292047, 2025). "In general, we unveil a novel pharmacological strategy for combating obesity-associated adipose tissue dysfunction by delineating a previously unrecognized mechanism through which ALM activates SIRT3 to orchestrate FUNDC1-mediated mitophagy." (PMID 41372934, 2025). "In contrary to its role in diabetic hearts, deficiency of FUNDC1 was found to accentuate obesity cardiomyopathy through regulation of mitochondrial Ca2+ integrity in an IP3R3-depednent manner." (PMID 35645834, 2022). "The protective role of FUNDC1 has also been reported in pathological conditions, including heart failure, cardiac aging, myocardial infarction, diabetes or obesity-associated complications." (PMID 35011599, 2021). "Recent research has linked the ablation of FUNDC1 to worsened obesity and insulin resistance from high-fat diets, demonstrating that FUNDC1 deficiency in white adipose tissue can impair mitophagy and mitochondrial function, leading to increased oxidative stress and inflammation." (PMID 39456203, 2024). "Likewise, FUNDC1 deficiency was shown to promote obesity, insulin resistance, MetS, cardiac remodeling, and even cell death due to defective control of mitochondrial quality." (PMID 35645834, 2022). "Moreover, previous reports showed that deficiency of FUNDC1 leads to mitophagy dysregulation, as it disrupts mitochondrial quality, which in turns aggravates obesity and instigates cardiac dysfunction." (PMID 35330106, 2022). "However, FUNDC1 deficiency decreases the susceptibility to high-fat-diet-induced obesity with improved insulin sensitivity and glucose tolerance." (PMID 32274386, 2020). "FUNDC1 knockout mice exhibit worsened obesity and IR under high-fat diets, linking impaired mitophagy to adipose metabolic dysfunction." (PMID 40866350, 2025). "This is supported by the notion that FUNDC1 maintains cross‐talk between skeletal muscles and fats to combat diet‐induced obesity, underscoring an intrinsic role for the mitophagy receptor in the governance of mitochondrial integrity and cell homeostasis." (PMID 40656543, 2025). "In an obesity-related study, FUNDC1 interacted with the related ubiquitin ligase complex receptor subunit to regulate IP3R2 receptor degradation, prevent calcium overload, and alleviate myocardial lipotoxic damage by mitochondrial autophagy." (PMID 40292006, 2025). "Under high-fat conditions, downregulation of the FUNDC1 gene inhibits the formation of MAMs, impairs the mitophagy mechanism, and leads to more severe obesity and IR." (PMID 38542170, 2024). "In high-fat-fed mice, specific deletion of FUNDC1 in adipocytes impaired mitophagy, exacerbating obesity and IR." (PMID 38542170, 2024). "It has been reported that FUNDC1 deletion mice fed an HFD exhibited obesity and IR, partly due to decreased mitophagy and mitochondrial quality in WAT, resulting in WAT remodeling and inflammation." (PMID 38812059, 2024). "Previous studies in animal models of (HFD)-induced obesity have reported that FUNDC1 knockout aggravated obesity and insulin resistance." (PMID 37173333, 2023). "KO of either Bnip3 or Fundc1 specifically in the liver or adipose tissue leads to damaged mitochondria accumulation, excess lipid deposition, and systemic insulin resistance and obesity." (PMID 35646940, 2022). "Activated FUNDC1-mediated mitophagy has been proposed to play protective roles in I/R injury, cardiac hypertrophy, and obesity-induced cardiomyopathy." (PMID 35096821, 2021). "In contrast to metabolic & cardiovascular diseases and obesity, the roles of FUNDC1, vary significantly among different cancers." (PMID 35011599, 2021).
Obesity (continued). "Pathophysiologically, FUNDC1 has been shown to play an important role in metabolic & cardiovascular diseases, obesity and cancer." (PMID 35011599, 2021). "Consistent to our data, deletion of the mitophagy receptor FUNDC1 exacerbates obesity-induced adipose tissue inflammation and glucose dysregulation." (PMID 34789781, 2021). "The physiological role of FUNDC1 has been studied in detail and it has been shown that FUNDC1 plays an important role in liver cancer and obesity." (PMID 32274386, 2020). "Obesity-related studies have shown that the mitochondrial autophagy receptor FUNDC1 interacted with the related ubiquitin ligase complex receptor, the subunit of which regulated IP3R2 receptor degradation, preventing calcium overload and alleviating myocardial lipotoxic damage." (PMID 40292006, 2025). "However, in skeletal-muscle specific FUNDC1 knockout mice, the obesity and systemic insulin resistance induced by high-fat diet are improved." (PMID 35959490, 2022). "Like the global knockout mice, Wu Hao’s study showed that severe mitochondrial abnormality, aggregated inflammation, obesity phenotypes, and insulin resistance phenotypes were observed when animals were fed high fat diet in the adipose tissue specific FUNDC1 knockout mice model." (PMID 35959490, 2022). "Based on the results of these studies, FUNDC1-related mitophagy regulates cardiac metabolism under obesity or HFD stress and may be a potential target to prevent obesity-associated cardiac injury." (PMID 35096821, 2021). "However, controversial finding was noted for the role of FUNDC1 under obesity-induced cardiomyopathy." (PMID 34975548, 2021). "FUNDC1-dependent mitophagy maintains adipose homeostasis, whereas FUNDC1 ablation in WAT disrupts mitochondrial integrity, exacerbates diet-induced obesity and IR." (PMID 40866350, 2025). "Deletion of Fundc1 induces defective mitophagy and impaired MQC, leading to more severe obesity and insulin resistance (IR) in mice fed a high-fat diet (HFD)." (PMID 38812059, 2024). "In contrast, a study found that mice lacking muscle FUNDC1 were found to have a protective effect against HFD-induced obesity, with improved insulin sensitivity and glucose tolerance despite reduced muscle mitochondrial energy." (PMID 35783853, 2022). "Whereas in obesity-induced cardiopathy, mitochondrial dysfunction and Ca2+ overload are worsened when FUNDC1 is absent in mice." (PMID 34975548, 2021). "Collectively, these results showed that Pink1/Parkin signaling, but not Fundc1 or Bnip3/Nix, was crucial for enhanced mitophagy in the heart or H9c2 cells in metabolic disorders during obesity." (PMID 34050133, 2021).
myocardial ischemia (16 papers, 2021 to 2025). A disorder of cardiac function caused by insufficient blood flow to the muscle tissue of the heart. "Endothelial-specific deletion of FUNDC1 eliminates the protective effects of exercise training, while overexpression of FUNDC1 protects aged mice from myocardial ischemia/reperfusion injury." (PMID 37583788, 2023). "Furthermore, EMPA treatment was reported previously to induce the autophagy process in a cardiac ischemia/reperfusion animal model via activation of the AMPK-α1/ULK1/FUNDC1 pathway." (PMID 38929110, 2024). "In this study, we observed in animal experiments that HA treatment associated with stimulation of FUNDC1-mediated mitophagy was protective against myocardial ischemia-induced HF, while FUNDC1 knockdown partially reversed the protective effect of HA on MI cytotoxicity." (PMID 35422895, 2022). "Current studies have shown that hypoxia-activated Fundc1-mediated mitophagy is essential for restoring mitochondrial function and cell/organelle balance in myocardial ischemia/reperfusion injury; moreover, emerging evidence suggests that autophagy is involved in cardioprotection." (PMID 35422895, 2022).
hepatocellular carcinoma (14 papers, 2020 to 2025). A malignant tumor that arises from hepatocytes. "A previous study in hepatocellular carcinoma also indicated the involvement of FUNDC1 in tumor progression and tumor immune microenvironment regulation." (PMID 39668821, 2024). "FUNDC1 overexpression correlates with poor prognosis and therapeutic resistance in various human malignancies, such as cervical cancer, laryngeal cancer, hepatocellular carcinoma, pancreatic cancer, and urothelial cancer." (PMID 39668821, 2024). "In cancer, FUNDC1 has dual roles in tumor progression at the initial stage of hepatocellular carcinoma (HCC) and suppresses tumorigenesis by inhibiting the inflammation response." (PMID 36831455, 2023). "A recent study found hepatocyte-specific FUNDC1 ablation accumulated dysfunctional mitochondria and triggers inflammasome activation, which suppresses human hepatocellular carcinomas initiation." (PMID 33972548, 2021). "FUNDC1 further suppresses hepatocellular carcinoma (HCC) initiation by attenuating inflammasome activation and inflammatory responses in hepatocytes; however, its upregulation at later stages of tumor progression may support tumor growth." (PMID 40750884, 2025). "FUNDC1 has also been reported to inhibit hepatocellular carcinoma (HCC) progression by suppressing activation of the inflammasome in mice." (PMID 35201480, 2021). "This was demonstrated using the diethylnitrosamine (DEN) mouse model of hepatocellular carcinoma (HCC), in which the mitophagy effector FUNDC1 was specifically deleted in hepatocytes leading to aberrant activation of the Nlrp3 inflammasome and IL-1β-driven hepatocyte hyperproliferation." (PMID 35517498, 2022). "FUNDC1 promotes the growth of hepatocellular carcinoma (HCC) tissues in the late stage of the disease, and the high level of FUNDC1 might also be a risk factor for HCC patients." (PMID 35959490, 2022). "Another study on a mouse model of human hepatocellular carcinoma (HCC), induced by the chemical carcinogen diethylnitrosamine (DEN), suggested that FUNDC1 suppresses HCC initiation by increasing mitophagy that reduced inflammasome activation and inflammatory responses in hepatocytes." (PMID 35011599, 2021). "In hepatocellular carcinoma (HCC), FUNDC1-mediated mitophagy suppresses early tumor initiation by inhibiting mtDNA/mtROS-induced inflammasome activation, while its upregulation in advanced stages may paradoxically support tumor growth." (PMID 41315223, 2025).
heart failure (12 papers, 2020 to 2024). Inability of the heart to pump blood at an adequate rate to meet tissue metabolic requirements. "For example, FUNDC1 deficiency caused heart failure in mice due to reduced MAMs formation and mitochondrial Ca2+ level; conversely, the heart function is restored in STZ-induced diabetes mellitus mice when FUNDC1 is deleted, owing to decreased MAMs formation and mitochondrial Ca2+ level." (PMID 34975548, 2021). "FUNDC1 is important in the heart and myocyte-specific FUNDC1 deletion in mice leads to cardiac dysfunction and heart failure." (PMID 37583788, 2023). "Compared with healthy group, the expression level of FUNDC1 and the number of SR-mitochondria contacts are dramatically reduced in heart failure patients." (PMID 36776252, 2023). "FUNDC1 mitophagy was found downregulated in pressure-overload induced heart failure, the effect of which was restored by α-LA treatment, in an ALDH2 dependent manner." (PMID 35645834, 2022). "The antioxidant α-lipoic acid (α-LA) exerts a regulatory role in heart failure and mitochondrial injury through FUNDC1." (PMID 36132224, 2022). "Further studies suggested that FUNDC1 knockout exacerbated AMI-induced heart failure by inhibiting MAMs formation." (PMID 35645834, 2022). "When subjected to acute myocardial infarction (AMI), FUNDC1 knocked-out mice exhibited worsened heart failure, shortened survival and greater mortality." (PMID 35645834, 2022). "The research above discusses the regulatory role of FUNDC1-mediated receptor-dependent autophagy in the pathology of heart failure and provides a good reference for future studies targeting mitophagy in heart failure." (PMID 36132224, 2022). "Here, we will review current progress regarding the role of FUNDC1 in mitophagy and MAMs formation and the occurrence of some CVDs, including heart failure, ischemia–reperfusion, metabolic cardiomyopathy, and sepsis-induced cardiomyopathy." (PMID 34975548, 2021). "ALDH2 activity and expression are restored by α-LA in TAC-induced heart failure model, which in turn increases the expression of FUNDC1 in a NRF1-dependent manner." (PMID 34975548, 2021). "Compared to healthy hearts, individuals with heart failure exhibit a more elongated morphology and reduced levels of MAM-associated proteins, including IP3R1, IP3R3, FUNDC1, phosphorylated CREB, and Fis1, resulting in a significant decrease in the proportion of adjacent ER to mitochondria." (PMID 38374992, 2024). "FUNDC1 could initiate mitophagy to eliminate damaged mitochondria, thereby protecting against I/R injury, cardiac remodeling, and heart failure." (PMID 37298100, 2023). "More importantly, the research showed that levels of FUNDC1 were significantly lower in patients with heart failure compared to control donors, meanwhile, contacts between the ER and mitochondria were reduced and mitochondria were more elongated in heart failure hearts." (PMID 35281107, 2022). "This supports the idea that FUNDC1 and MAMs are involved in the development of heart failure." (PMID 35645834, 2022). "Moreover, FUNDC1 also plays important role in pressure overload-induced left ventricular hypertrophy and dysfunction and alpha-lipoic acid (α-LA) reduces the degree of transverse aortic constriction (TAC)-induced heart failure in a FUNDC1-related manner." (PMID 34975548, 2021). "In our study, we found that FUNDC1 was downregulated in pressure-overload induced heart failure." (PMID 32732978, 2020). "The results indicate that the expression of FUNDC1 is elevated in MCM but reduced in instances of cardiac remodeling, heart failure, and myocardial IR injury, with divergent impacts on mitochondrial function among distinct HDs." (PMID 37298100, 2023). "In this review, we examined the molecular structure of FUNDC1 and outlined its cellular function in the MQC system, highlighting its protective role in cardiac remodeling/heart failure and cardiac I/R injury." (PMID 37298100, 2023).
heart failure (continued). "A role for FUNDC1 in CVD has generated much recent attentions, in particular in myocardial ischemia/reperfusion, heart failure, septic cardiomyopathy, metabolic syndrome and other common CVD." (PMID 35645834, 2022). "The expression of FUNDC1 was found to be significantly reduced in patients with heart failure, as opposed to those with diabetes." (PMID 37298100, 2023). "The experimental results suggest that DQP may improve mitochondrial energy metabolism by improving FUNDC1-mediated mitophagy through the interaction mechanism of ULK1 and PGAM5, thereby treating heart failure." (PMID 36132224, 2022). "However, in addition to the FUNDC1-mediated receptor-dependent autophagy, the PINK1/Parkin pathway-mediated receptor-independent mitophagy in heart failure deserves further attention." (PMID 36132224, 2022). "However, whether the protective effect of HA treatment on MI-induced heart failure was reversed after FUNDC1 knockdown was not further confirmed in an in vivo model." (PMID 35422895, 2022).